IL17A (interleukin 17A)
Diseases named in the same sentence as IL17A in open-access papers (continued):
Sharing a sentence is not in itself a finding about the gene and the disease.
colitis (continued). "Similar to the in vivo blockade experiments, neutralization of IL-17A or IL-22 was only effective in Tbx21−/− T cells suggesting that augmented cytokine production may be a major driver in colitis induced by T-bet-deficient T cells." (PMID 27193261, 2016). "Since both Th1 and Th17 cells are associated with colitis, we investigated whether Tpl2 altered the proportions of IFNγ or IL-17A positive CD4 T cells within the spleen and mesenteric lymph nodes (MLN)." (PMID 25781948, 2015). "Thus, in dextran-sodium sulfate (DSS) colitis, both protective 91, 92 and pathogenic roles 93 for IL-17A have been documented." (PMID 23405904, 2013). "In addition, the HF-FO diet reduced both colitis-associated disease severity and colonic mRNA expression of the Th17 cell master transcription factor (RORγτ) and critical cytokines (IL-6, IL-17A, IL-17F, IL-21, IL-23 and IFNγ) versus HF (P<0.05)." (PMID 23166761, 2012). "However, Il-17f−/− mice were resistant to dextran sulfate sodium (DSS)-induced colitis, while Il-17a deficiency exacerbated this disease." (PMID 22509371, 2012). "Using the AOM + DSS model, Hyun and colleagues showed that IL-17A-deficient mice developed a less severe colitis than wild-type mice, as demonstrated by the decreased cell infiltrate and the diminished expression of pro-inflammatory factors (e.g., TNF-α, IL-6)." (PMID 23109839, 2012). "Indeed, it was shown that adoptive transfer of IL-17A-deficient naïve CD4+ T cells to recipient immunodeficient mice results in severe colitis." (PMID 22082127, 2011). "Neutrophil-depleted mice developed more severe colitis than controls, characterized by significant weight loss, aggravated histological lesions, impaired mucosal barrier function, and expression of proinflammatory cytokines (e.g., IL-1β, IL-17A, IFN-γ and TNF-α) in the colon tissues." (PMID 36729914, 2023). "IL-17A inhibition may have dual effects, alleviating inflammation, but also damaging the function of already impaired intestinal epithelial barrier, causing colitis." (PMID 35754494, 2022). "IL-17A was shown to be a key cytokine in colitis, further supporting our hypothesis that the increase in IL-17A secretion by CD5-deficient T cells, secondary to increased Stat3 phosphorylation, is causal for the disease phenotypes we observed in CD5 KD NOD mice." (PMID 35720357, 2022). "Importantly, in a double-blinded clinical trials, targeting IL-17A or IL-17R was ineffective to treat Crohn’s disease, rendering higher risk of adverse events, indicating a protective role of IL-17A in colitis studies, which highlight the protective role of IL-17A in the IBD." (PMID 32391010, 2020). "In contrast, in vivo-activated Nfat-deficient CD4 T cells were skewed toward increased IFNγ and IL-17A expression, and T cell-restricted Nfat5-deficient mice exhibited more severe pathology and enhanced IFNγ mRNA expression in lymph nodes and colon of an animal model of experimental colitis." (PMID 30538703, 2018). "Moreover, IL-17A deficiency was associated with decreased colitis-associated carcinogenesis." (PMID 30186819, 2018). "Therefore, the enhanced susceptibility to DSS colitis in AhRRE/E mice may be caused by the elevated frequency of Th17 as well as Tc17 cells in agreement with the pathogenic role of IL-17A production in the DSS colitis model." (PMID 27184933, 2016). "Having characterized a Tpl2-dependent defect in IL-17A expression, along with the previously identified IFNγ defect, we next examined the capacity of Tpl2−/− T cells to induce disease in a T cell transfer model of colitis associated with a mixed Th1 and Th17 inflammatory response." (PMID 25781948, 2015). "It has been shown that NRP1 modulates and enhances the capacity of ILC3s to produce the pro-inflammatory cytokine IL-17A, thereby directly promoting and exacerbating colitis." (PMID 41465029, 2025).
colitis (continued). "Particularly, the direct administration of exogenous cytokines (IL-17A or IL-22) inhibits chemokine expression in the colon tissues and partially protects the mice against colitis, consistent with the resistant phenotypes observed in the chemokine KO mice." (PMID 40749055, 2025). "Our previous findings demonstrate EBV DNA’s significant role in exacerbating colitis symptoms and elevating the levels of the pro-autoimmune cytokine interleukin-17A (IL-17A) in an IBD mouse model via toll-like receptor 9 (TLR9)." (PMID 40722611, 2025). "NRP1 blockade ameliorates colitis in preclinical models by limiting IL-17A production and altering microbiota composition." (PMID 40963622, 2025). "Similar to Itch−/− Th17 cells, when adoptively transferred, Ndfip1 deficient Th17cells produced more IL-17A and induced severe colitis, indicating a pivotal role for the NDFIP1-ITCH pathway in the regulation of IL-17A-mediated inflammation." (PMID 40821838, 2025). "To evaluate the differentiation of Th17 cells in vivo, we used the dextran sulfate sodium (DSS)-induced colitis model in IL-17A-GFP reporter mice." (PMID 40422192, 2025). "In DSS colitis, Arg-1 deletion in myeloid cells attenuated the protective role of MDSCs during colitis by upregulating IL-17A and IL-17F, while the adoptive transfer of suppressive MDSCs alleviated colitis in ArgmyeKO mice." (PMID 40244120, 2025). "Another recently developed BsAbs is FL-BsAb1/17, targeting IL-1β and IL-17A; it was compared to etanercept in a recent study, showing potential to become a new dual-target candidate for colitis treatment." (PMID 40001525, 2025). "NCR- ILC3s contribute to colitis via IL-23-driven IL-17A secretion, which recruits neutrophils and exacerbates epithelial barrier damage." (PMID 40963622, 2025). "Although IL-17A contributes to colitis and cancer development, it is also critical for intestinal tissue repair, epithelial permeability, and barrier function." (PMID 40749055, 2025). "In a transfer‐induced colitis model, Rag1–/– mice receiving Nfkbid knockout T cells developed a more severe form of colitis, characterized by an increase in IFN‐γ+ T cells and a complete loss of IL‐17A‐producing cells." (PMID 40359334, 2025). "Paradoxically, IL-17A knockout mice exhibit exacerbated colitis, suggesting a protective role in epithelial repair." (PMID 40408459, 2025). "On the other hand, neutralization of both IL-17A and IL-17F ameliorated colitis at early administration, but administration of IL-17A or IL-17F did not." (PMID 40565877, 2025). "In our study, DSS-induced colitis skewed splenic T cells and was characterized by elevated Th17 cell frequencies and increased IL-17A production." (PMID 40298818, 2025). "Conversely, certain findings indicate that IL-17A/F can exacerbate colitis induced by adoptive transfer of naïve T cells or TNBS treatment." (PMID 39379604, 2024). "When cotransferring naive T cells from IL-27rα−/− mice with B cells from WT mice into B6 DKO mice, there was severe colitis, and IFNγ and IL-17A expression in colonic tissue explants was increased and IL-10 expression was reduced." (PMID 38566992, 2024). "A mouse strain, in which tdTomato and enhanced green fluorescent protein were under the control of the Foxp3 promoter and Il17a promoter, was established and subjected to colitis induction with dextran sulfate sodium." (PMID 38415949, 2024). "N. brasiliensis‐derived EVs were used as treatment in a mouse model of chemical‐induced colitis and demonstrated to reduce IL‐6, IL‐1β, IFNγ and IL‐17a and increase IL‐10 expression." (PMID 39113589, 2024). "In animal models of ETBF-induced tumorigenesis, the BFT was shown to exacerbate colitis in tumorigenesis by promoting the production of the inflammatory cytokine interleukin-17A (IL-17A) and CXCL1 in the host." (PMID 39330861, 2024).
colitis (continued). "The naive and all primed cADSCs consistently reduced the frequency of CD4+ IL-17A+ Th17 cells increased by colitis induction, similar to the suppression pattern in Th1 cells, and especially cADSCs primed with colon homogenate significantly reduced Th17 cells." (PMID 39176394, 2024). "Our findings indicated that GPX4 mediated ILC3s, particularly the NKp46+ILC3 subpopulation, specifically regulating colitis, accompanied by alterations in ferroptosis characteristics of ILC3s and their secretion capacity for IL-22 and IL-17A." (PMID 39300068, 2024). "Compared to the levels in the normal group, the proinflammatory cytokines (e.g., IFN-γ, TNF-α, IL-17A, IL-1β and IL-6) were significantly elevated in the colitis group, suggesting that mice bearing colitis have an increase in proinflammatory cytokines." (PMID 38396052, 2024). "In this study, we showed that CAPE treatment reduced ETBF-mediated colitis by downregulating the expression of IL-17A and CXCL1 in mice." (PMID 39330861, 2024). "Our study also showed a significant increase in colonic expression of interleukin-17A (IL-17A), as well as interferon γ (IFNγ) and tumor necrosis factor α, during colitis in mPGES-1−/− mice compared with that in WT mice." (PMID 39596393, 2024). "Arg-1+ MDSCs have even modulated Th17 cell polarization to enhance IL-17A secretion, thereby attenuating the immune response and alleviating colitis." (PMID 37733169, 2024). "For example, in a DSS-induced colitis model, IL-22, IL-17A, and GM-CSF play suppressive roles in colitis, suggesting their beneficial effects on IECs." (PMID 39379604, 2024). "In the first patient, who had a history of SAPHO syndrome, severe colitis developed after 3 months of exposure to the IL-17A inhibitor." (PMID 38060157, 2024). "Here, we present two cases of different forms of colitis that occurred during treatment with two IL-17A inhibitors, secukinumab and ixekizumab." (PMID 38060157, 2024). "In colitis mouse models, transferring WT Treg cells was capable of suppressing colitogenic T-cell expansion and inflammatory cytokines IL-17A and IFNγ expression." (PMID 38566992, 2024). "IL-23-driven IL-17A+ IFN-γ+ Th cells or exTh17 cells are believed to be highly pathogenic T-cell populations implicated in the development and exacerbation of colitis." (PMID 39379604, 2024). "Collectively, C. tropicalis MYA-3404 uses nicotinamidase, at least partially, to alter nicotinamide metabolism, and thus, protect mice from experimental colitis by inducing IL-17A expression and promoting epithelial cell proliferation in the colon." (PMID 39462273, 2024). "IL-17A inhibition decreases acute colitis inflammation but can reinforce tight junctions and protect epithelial cells." (PMID 39364475, 2024). "Surprisingly, we also observed an increase in Il17a expression in the lungs of TCRδ-/- mice with colitis." (PMID 37063825, 2023). "In tumor-bearing mice, colitis-related IL-17A significantly suppressed the extravasation and self-renewal of the stem-like subset, dampening CTL-conferred antitumor immunity." (PMID 37605139, 2023). "The blockade of IL-17A by anti-IL-17A antibodies aggravates disease severity in DSS-induced colitis." (PMID 37239894, 2023). "Ayane Mikami found that Flavonifractor is able to help reduce intestinal inflammation in DSS-mediated colitis mice through inhibiting IL-17A." (PMID 37111225, 2023). "constructed a DSS-induced colitis model in mice and reported that blocking IL-17A can inhibit DSS-induced UC." (PMID 38045694, 2023). "On the stem-like CTLs, we detected lower levels of LFA-1 expression, and the surface LFA-1 expression was further reduced by colitis-induced IL-17A." (PMID 37605139, 2023). "It is demonstrated that in colitis pathology, both IL-17A and IL-17F are involved in developing intestinal inflammation because these cytokines have overlapping or interdependent pro-inflammatory role." (PMID 37344888, 2023).
colitis (continued). "Activated T cells produce IFNγ and/or IL-17 A in the colonic LP of the T cell transfer colitis model." (PMID 38012544, 2023). "Although IL-17A and IL-17F are the important inflammatory cytokines, their function in colitis development is still debatable." (PMID 36792629, 2023). "Colitis-induced IL-17A profoundly reduced LFA-1 expression on the stem-like subset, but minorly affected LFA-1 on the terminally exhausted CTLs." (PMID 37605139, 2023). "When the colitis mice were treated with a neutralizing antibody against IL-17A (αIL-17A), tumor growth was significantly inhibited compared with the mice that were treated with isotype IgG." (PMID 37605139, 2023). "Transcription of IL-6 cytokine increased by 11.7-folds, and IL-17A increased by 6.3-folds in the colitis tissues of ICB-treated patients with irEC." (PMID 37605139, 2023). "We inoculated CT26.CL25 cells into female BALB/c mice, induced colitis, and administrated neutralizing antibody against PD-1 (αPD-1), against IL-17A (αIL-17A), or against both (αPD-1 + αIL-17A)." (PMID 37605139, 2023). "In our study, IL-1β, TNF-α, IL-6, and IL-17A contents within the colon increased after CR infection, conforming to prior research regarding CR-induced colitis." (PMID 37111225, 2023). "Another limitation is that the IL-17A+ILC3s-dependent pattern of 12-KLCA alleviating colitis requires in-depth validation by cell adoptive transfer or antibody neutralization." (PMID 38062857, 2023). "Elevated Th17 cells are associated with the pathogenesis of inflammatory bowel disease (IBD) and colitis through expressing rorγt, IL-17A, IL-17F, and IL-21 in the inflamed mucosa." (PMID 37344888, 2023). "CD90-negative and CD90-low CD127+ ILC were a potential source of IL-13, IFNγ and IL-17A at steady state and upon dysbiosis- and dextran sulphate sodium-elicited colitis." (PMID 37114052, 2023). "Flow cytometry analysis demonstrated that, after the development of colitis, the eEF2K knockout group had higher populations of IL-17A+ CD4+ T cells in the colons compared to the WT group." (PMID 37875468, 2023). "More IL-17A-producing cell numbers were detected in the colons of colitis mice, with about 3.2-folds of increase as a comparison to normal mice." (PMID 37605139, 2023). "Collectively, these findings demonstrate that both IL-17A and IL-17F serve as the downstream targets of Nsun2 in Th17 cells and participate in the progression of colitis." (PMID 36792629, 2023). "We have previously shown that spontaneous colitis in Tbx21-/- x Rag2-/- ulcerative colitis (TRUC) mice is partially driven by IL-17A-producing CD90+ ILC." (PMID 37114052, 2023). "In an animal model of TNBS-induced colitis, butyrate suppressed IL-17A production by disrupting the Treg/Th17 balance." (PMID 38203534, 2023). "We provided an option by neutralizing IL-17A to improve ICB-based therapeutic efficacy when abnormal IL-17A generation in the setting, such as colitis, occurred during cancer treatment." (PMID 37605139, 2023). "Meanwhile, this finding was also confirmed by a drastic decrease of IL-17A+ILC3s in the colon of colitis mice receiving 12-KLCA compared with the DSS group." (PMID 38062857, 2023). "The closely correlated pro-inflammatory cytokines in lipid metabolism are TNF-a, IL-17a, IL-4, and IL-6, and these molecules promote colitis progression." (PMID 37569708, 2023). "In support, our findings demonstrated that blocking of both IL-17A and IL-17F had the most prominent effect on alleviation of colitis development, even though interfering either one also showed beneficial outcome." (PMID 36792629, 2023). "In BALB/c background mice, CD90- ILC accounted for about a fifth to a third of cLP ILC, and we detected a substantial amount of IFNγ, IL-13 and IL-17A production by these cells in the context of DSS- or dysbiosis-elicited colitis." (PMID 37114052, 2023).
colitis (continued). "Administration of anti-IL-17A neutralizing antibody to the colitis mice restored the CTL tumor infiltration and enhanced anti-PD-1 treatment efficacy against tumors." (PMID 37605139, 2023). "Increased disease scores and symptoms were also observed in DSS-induced colitis upon the blockade of IL-17A or in IL-17 KO mice." (PMID 36769019, 2023). "Experimental studies on mouse models show an exacerbation of colitis following IL-17A or IL-17RA blockade." (PMID 37631384, 2023). "As previously reported, the mRNA levels of inflammatory cytokines, Il6 (the gene encoding interleukin 6 (IL-6), Il17a, Tnf (the gene encoding tumor necrosis factor α), and Il1b, were increased in the colon of Vdr(+/−) mice with DSS-induced colitis." (PMID 36834927, 2023). "Nsun2 deficiency in Th17 cells impairs the stability of m5C-modified mRNAs, such as Il17a and Il17f, resulting in ameliorated colitis progression induced by Th17 cells." (PMID 36792629, 2023). "An overexpression of miR-425 promotes Th17 cell production and IL-17A secretion by suppressing FOXO1 in colitis mice." (PMID 37834058, 2023). "We have demonstrated the importance of Th17’s effector cytokines in the pathogenesis of colitis by the administration of neutralizing IL-17A to the mutant mice, which resulted in improved intestinal morphology and clinical scores." (PMID 35393949, 2022). "IL-17A knockouts showed a reduced degree of inflammation than wild-type when colitis was induced using the DSS." (PMID 35465355, 2022). "Compared with the normal group, TNF-α, IL-β, IFN-γ and IL-17A obviously increased in colitis tissues." (PMID 35372817, 2022). "Mice with a myeloid-specific deletion of TSC1 gene (TSC1cKO) displayed severe dextran sodium sulfate (DSS)-induced colitis accompanied by high levels of IL-17A, IL-17F, and IFN-γ." (PMID 36465179, 2022). "We also observed that DSS‐induced colitis in Il34−/− rats led to increased levels of pro‐inflammatory cytokines Il6, Il1b, Il22 and a trend for an increase for Il17a, all involved in gut inflammation, whereas Ifng was decreased." (PMID 36030499, 2022). "CD69+CD103− CD4+ TRM cells are the major source of IL-17A production in the colon of mice with DSS-induced colitis." (PMID 35844584, 2022). "The resistance of YFP+ cells to IL‐17A production, thus, correlates with the lower levels of colitis induced by naïve‐like YFP+ cells compared to their YFP– counterparts." (PMID 35092032, 2022). "Systemic CDK9 inhibition led to histological improvement of immune-mediated colitis and was associated with targeted suppression of colonic CD4+ T cell-derived IFN-γ and IL-17A." (PMID 35660024, 2022). "DSS treatment induces Th17 cytokines (such as IL-17A) and Th1 cytokines (including IFNγ and IL-2) in the colon, and these cytokines are essential for developing colitis." (PMID 34983695, 2022). "We also found that mEVs decreased the expression of pro-inflammatory factors (IL-1β, IL-6 and IL-17A) in colitis." (PMID 35893911, 2022). "In summary, STAT3 GOF Tregs improved survival in a mouse model of experimental colitis, despite impaired Treg recovery and control of Ly5.1+ T cell accumulation and IL-17A secretion." (PMID 36136607, 2022). "To understand the importance of Th17 effector cytokines in the pathogenesis of colitis, we administered anti–IL-17A (αIL-17A) neutralizing antibody or IgG1 control concurrently with CO or TAM for 5 consecutive days in Klf5ΔIND mice." (PMID 35393949, 2022). "To clarify the role of Th17 cells in the development of colitis, we crossed Rap1KO mice with IL-17A KO mice (double knockout mice; DKO)." (PMID 35246619, 2022). "Here, we showed that TIGIT was required for IL-17A production by CD69+CD103− CD4+ TRM cells during DSS-induced colitis." (PMID 35844584, 2022). "CD69+CD103− CD4+ TRM cells accounted for 62.9% and 72.5% of IL-17A+ CD4+ T cells in the colon of DSS-induced colitis or control mice, representing the major source of IL-17A production." (PMID 35844584, 2022).